FANCM (FA complementation group M)
Diseases named in the same sentence as FANCM in open-access papers (continued):
Sharing a sentence is not in itself a finding about the gene and the disease.
Lynch syndrome (3 papers, 2019 to 2021). An autosomal dominant hereditary neoplastic syndrome characterized by the development of colorectal carcinoma and a high risk of developing endometrial carcinoma, gastric carcinoma, ovarian carcinoma, renal pelvis carcinoma, and small intestinal carcinoma.
premature ovarian failure (3 papers, 2021 to 2025). "It was reported that females with bi-allelic LoF variants in FANCM presented with premature ovarian failure (POI)." (PMID 34976027, 2021). "Furthermore, FANCM (OMIM: 609644) is linked to autosomal-recessive premature ovarian failure and spermatogenic failure." (PMID 39979679, 2025). "In women, FANCM and FANCL mutations have been associated with premature ovarian failure." (PMID 41488147, 2025).
prostate carcinoma (3 papers, 2022 to 2025). A carcinoma that arises from epithelial cells of the prostate gland. "For likely pathogenic mutations, FANCM and FH ranked top for kidney cancer, RAD51C ranked top for bladder cancer, and ATM and PMS2 ranked top for prostate cancer." (PMID 36451132, 2022).
female infertility (2 papers, 2021 to 2022). Diminished or absent ability of a female to achieve conception. "Consistent with the mice model, bi-allelic FANCM PV was also associated with both male and female infertility in humans." (PMID 34976027, 2021). "Previous studies found that the FANCM gene was associated with Non-obstructive Azoospermia and ovarian deficiency, which led to male/female infertility." (PMID 35847642, 2022).
glioma (2 papers, 2022 to 2026). A benign or malignant brain and spinal cord tumor that arises from glial cells (astrocytes, oligodendrocytes, ependymal cells).
leukemia (2 papers, 2017 to 2021). A malignant (clonal) hematologic disorder, involving hematopoietic stem cells and characterized by the presence of primitive or atypical myeloid or lymphoid cells in the bone marrow and the blood. "The carrier (OCJ19) of FANCM rs144567652 was diagnosed with OVCA at 49 years of age and had a family history of breast (n = 2), multiple myeloma, leukemia, and ovarian, all on the maternal side of her family." (PMID 28591191, 2017).
lung carcinoma (2 papers, 2018 to 2021). "As for the genetic landscape in detail, several incidences of mutated genes that were adverse to prognosis were observed to be lower in the young lung cancer group (LRP1B, SMARCA4, STK11, FAT2, RBM10, FANCM), which may explain the better prognosis of the young lung cancer group to some extent." (PMID 35096611, 2021).
melanoma (2 papers, 2012 to 2023). A malignant, usually aggressive tumor composed of atypical, neoplastic melanocytes. "Similarly, FANC proteins including FANCM were found to be transcriptionally upregulated in melanomas." (PMID 22848695, 2012).
serous ovarian cancer (2 papers, 2017). "Previous studies on FANCM mutations have shown similar results; however, a very recent study found significant association between FANCM mutations and high grade serous ovarian cancer." (PMID 28702895, 2017).
spermatogenic failure (2 papers, 2019 to 2022). A male infertility characterized by dirsuption of the process of sperm development from diploid cells into mature haploid spermatozoa. "In the current study, we identified an autosomal recessive FANCM p.P648Lfs*16 PV in a first-cousin marriage family, which was homozygous in three infertile brothers with spermatogenic failure and heterozygous in their parents." (PMID 29895858, 2019).
breast tumors (1 paper, 2019). "As this is consistent with previous results, PARP1 inhibition might be a possible therapeutic approach to treat patients with breast tumors associated with germline FANCM pathogenic variants." (PMID 31700994, 2019).
chordoma (1 paper, 2023). Chordomas are rare malignant tumors arising from embryonic remnants of the notochord in axial skeleton. "Genes were selected to represent both those functionally connected to other chordoma dependency genes (PTPN11, FANCM, ADAR, PRKRA, SOX9, SRRM2, SLC2A1, and SLC7A5), as well as those with putatively unique effects (LUC7L2 and CDK6)." (PMID 37024492, 2023).
endometrial cancer (1 paper, 2025). Primary or metastatic malignant neoplasm involving the endometrium (mucous membrane that lines the endometrial cavity).
familial breast cancer (1 paper, 2017). "Here, we studied the prevalence of three other FANCM variants: c.5791C>T, which has been reported to predispose to familial breast cancer, and the c.4025_4026delCT and c.5293dupA variants recently identified in Finnish cancer patients." (PMID 28702895, 2017).
invasive breast carcinoma (1 paper, 2017). A carcinoma that infiltrates the breast parenchyma. "We genotyped the FANCM c.5791C>T mutation in 4806 invasive breast cancer patients, including BRCA1/2 mutation negative familial cases and unselected cases, and in 2734 healthy population controls from four different geographical areas of Finland." (PMID 28702895, 2017).
invasive ductal carcinoma (1 paper, 2018). "The woman carrying the nonsense mutation FANCM:c.1972C > T was diagnosed with invasive ductal carcinoma at the age of 62." (PMID 29351780, 2018). "The second woman carrying FANCM:c.1491dup was diagnosed with invasive ductal carcinoma at the age of 63." (PMID 29351780, 2018).
primary ovarian insufficiency (1 paper, 2021). "Mutations in several DNA damage response and repair genes, including FANCM and BRCA1/2 as well as meiosis-specific homologous recombination genes (MSH5, RAD51), are implicated in primary ovarian insufficiency." (PMID 33500205, 2021). "Specifically, mutations in FANCM as well as FANCA, BRCA1/FANCS and BRCA2/FANCD1 are associated with premature ovarian insufficiency." (PMID 33500205, 2021).
squamous cell carcinoma (1 paper, 2025). A carcinoma arising from squamous epithelial cells. "Individuals with biallelic FANCM gPVs have been observed to develop several types of cancer including breast- and squamous cell carcinoma at a young age." (PMID 39979679, 2025).
uterine cancer (1 paper, 2020). Primary or metastatic malignant neoplasm involving the uterine corpus and/or the cervix. "All of the CRC cases assayed in the two pedigrees carry the rare FANCM variant, as do some cases of other cancers, including lung, breast, prostate, pancreas, and uterine cancer cases." (PMID 33118316, 2020).
valvular heart disease (1 paper, 2019). "However, the youngest brother (IV:4) in this family also died of valvular heart disease and he was heterozygous for the FANCM PV." (PMID 29895858, 2019). "Given the consanguinity of this family, it can be inferred that some other PV, at least not the homozygous FANCM PV alone, contributed to the valvular heart disease in IV:2." (PMID 29895858, 2019).
cancer (65 papers, 2011 to 2026). A tumor composed of atypical neoplastic, often pleomorphic cells that invade other tissues. "Such correlations would be particularly valuable given FANCM’s emerging role as a cancer predisposition gene and its synthetic lethal interactions with multiple DNA repair pathways." (PMID 40447800, 2025). "Somatic mutations in FA core complex and FANCM complex factors are also found in 6.58% of all cancer samples from the TCGA cohort, with a significant proportion harbouring two or more mutations, allowing for potential compound heterozygous effects." (PMID 41006228, 2025). "Both studies exploited the intrinsic predisposition of ALT cancer cells to replication stress by depleting FANCM or through pharmacological inhibition of FANCM-BLM interaction, resulting in synthetic lethality." (PMID 32962238, 2020). "Of those listed, ERCC3, FANCA and FANCM LoF variants are good candidates for further research as potential cancer-susceptibility mutations as the normal functions of their gene products are in DNA repair pathways." (PMID 26023681, 2015). "The significance of this interface became clear when we examined cancer-associated FANCM variants." (PMID 40447800, 2025). "Heterozygous germline mutations of FA genes, which include FA core complex genes and FANCM, have been associated with predisposition to cancers, while homozygous deletions, somatic mutations and gene silencing of FA genes are also a common feature of many cancers." (PMID 41006228, 2025). "At the same time, FANCM variants are known to be associated with cancer predisposition." (PMID 38927643, 2024). "Our case report raises a novel possibility that the infertile carriers of FANCM gene missense variants could also be prone to cancer development." (PMID 38927643, 2024). "Therefore, the possibility of distinct roles of FANCM in normal and ALT-exhibiting cancer cells, as well as the significance of the p.Q1701* and other truncating FANCM mutations in cancer remain to be elucidated." (PMID 32680567, 2020). "While ATM, BRCA, and POLQ mutations were similarly prevalent in both cancer types, adenocarcinoma patients had a high frequency to mutations effecting FANCM (8.9%) and FANCD2 (5.6%), comprising a majority of the difference between the two cancers in overall HR mutation rate." (PMID 33214570, 2020). "Notably, biallelic mutations in certain FA pathway genes, such as FANCS/BRCA1, FANCO/RAD51C, FANCR/RAD51, and FANCM can cause an FA-like disorder that shares the cancer predisposition of classical FA and, in some cases, the associated developmental abnormalities, but lacks bone marrow failure." (PMID 41155398, 2025). "Jeitany and colleagues identified gapmer antisense oligonucleotides that target FANCM, a key therapeutic candidate in cancer cells utilizing alternative lengthening of telomeres (ALT) mechanisms." (PMID 40125273, 2025). "Emerging evidence also points to additional FA genes, such as RAD51D, FANCM, and FANCJ/BRIP1, as contributors to cancer risk in the heterozygous state." (PMID 41155398, 2025). "For instance, disrupting FANCM’s ATPase activity or MM2 domain has shown therapeutic potential in ALT-positive cancers." (PMID 40447800, 2025). "Overall, our study validates the essential role of FANCM for ALT cancers in vivo and proposes FANCM-targeting ASOs as an effective strategy for anti-ALT therapies." (PMID 40125273, 2025). "Overall, a germline pathogenic variant (gPV) in a cancer predisposing gene was identified in 9.7% of individuals (CHEK2, FANCM, NF1, POT1 and PTEN) and a candidate variant in 4.2% of individuals (HOXB13, MAX and RECQL4)." (PMID 39979679, 2025). "Cancer patients with tumors with wildtype FANCM and low expression of TONSL-MMS22L have a more favorable prognosis than those with high expression." (PMID 41030968, 2025). "FANCM has emerged as a promising therapeutic target in cancer treatment, owing to its synthetic lethal interactions with various DNA repair pathways and its crucial role in ALT." (PMID 40447800, 2025).
cancer (continued). "FANCM acts as an anchor for DNA repair complex; pharmacological inhibition of FANCM was selectively toxic for cancer cells that use alternative lengthening of telomeres." (PMID 37297004, 2023). "In 2019 the Pickett lab showed that ALT cells are hypersensitive to replication stress caused by FANCM depletion, compared to telomerase-positive cancer cells, highlighting FANCM as an ALT therapeutic target." (PMID 36833275, 2023). "In recent years, a few groups, including ours, identified FANCM as a promising molecular target for treating ALT+ cancers." (PMID 37372458, 2023). "Efforts to disrupt the FANCM–BTR interaction as a means to inhibit ALT cancer cell growth are preliminary, but the strategy appears promising." (PMID 35259951, 2022). "In AYA BRCA we identified more frequent FANCM, FANCD2, and BRCA1 mutations when controlling for TMB, suggesting the role of DNA damage repair in this cancer type." (PMID 36433963, 2022). "The inhibition of FANCM was previously shown to induce a potent acute apoptotic phenotype in ALT cancer cell lines, suggesting its potential as an anticancer target in ALT." (PMID 34743173, 2021). "The cancer genome spectrum showed sarcomatoid HCC group had significant higher mutation rates in CDKN2A, EPHA5, FANCM and MAP3K1." (PMID 34331411, 2021). "Depletion of FANCM in these cells induced reduced cell viability, and hence FANCM inhibition has been proposed as therapeutic strategy specifically in cancer cells with ALT." (PMID 32680567, 2020). "These cancers also had high rates of ATM, POLQ, FANCM mutations, as well as those to several other genes." (PMID 33214570, 2020). "Intriguingly, patients carrying FANCM mutation don’t exhibit clinical symptoms that define FA such as congenital malformations and BMF and are just characterized by infertility and cancer predispositions." (PMID 32962238, 2020). "We also discuss how FANCM can and has been targeted in cancer cell killing, including potential opportunities in ALT and other genetic backgrounds." (PMID 31663812, 2019). "FANCM essentiality for ALT cell viability was further confirmed by interrogating publicly available catalogs of CRISPR/Cas9 gene knock-outs across cancer cell lines." (PMID 31552268, 2019). "In several recent studies, we and others demonstrate that expression and activity of FANCM, a DNA translocase protein, is essential for the viability of ALT-associated cancers." (PMID 31663812, 2019). "Here we provide a summary of how and why FANCM depletion leads to deletion of ALT-controlled cancers, predominantly through a hyper-activation of break-induced replication." (PMID 31663812, 2019). "Our data demonstrate a particularly potent strategy for killing ALT cancer cells, through targeting the FANCM-BTR interaction." (PMID 31138797, 2019). "It is worth noting that although LOH in cases with BRCA1 and BRCA2 truncations mutations were largely restricted to OV and BRCA, the majority of LOH truncations in other genes (for example, ATM, PALB2, BAP1, FANCM) were found across cancer types." (PMID 26689913, 2015). "FANCG, PALB2 and SLX4 homozygous deletions are identified in single carcinomas while FANCM homozygous deletions are identified in 2 carcinomas." (PMID 26438152, 2015). "Of 608 cancer-related genes, 32 including RON/MISTR1, ATM (ataxia teleangiectasis mutated) and FANCM (Fanconi anemia M protein) were affected by amiloride." (PMID 21694768, 2011). "FANCM was assigned the prefix FANC before biallelic pathogenic variants in FANCM were shown much later to be associated with cancer but not with physical FA phenotypes." (PMID 40232843, 2025). "Pedigree studies based on the UPDB have previously provided the identification of BRCA1 and BRCA2, and more recently have identified additional rare cancer predisposition variants (GOLM1; CELF4; FANCM; ERF; LRBA; FGF5) in similar sets of sampled high-risk pedigrees." (PMID 38136396, 2023).
cancer (continued). "However, FANCM depletion in normal and telomerase-positive cells does not promote ALT activity of induce cell cycle arrest, making FANCM a candidate for ALT cancer therapeutics." (PMID 37046606, 2023). "The strong biological foundation that supports induction of telomere-specific replication stress as a rapid and potent means to destroy ALT cancer cells implicates proteins such as FANCM and SMARCAL1 as potential targets for the development of ALT therapeutics." (PMID 35259951, 2022). "Furthermore, the disruption of FANCM function using a small molecule inhibitor has been shown to be selectively detrimental to ALT cancer cells." (PMID 35259951, 2022). "Identified monoallelic variants in genes linked to autosomal recessive predisposition to cancer such as the ones in RAD50, FANCC, and FANCM might also be relevant for cancer risk." (PMID 35250968, 2022). "Importantly, FANCM is a helicase/translocase and thus considered to be a druggable target for cancer therapy." (PMID 34663427, 2021). "FANCM is a FA helicase that is essential for the viability of ALT cancer." (PMID 34743173, 2021). "Several previous studies have suggested that inhibition of FANCM function could be used as a mechanism of cancer-specific cell killing." (PMID 31138797, 2019). "One possible caveat comes from the observations that human FANCM mutants might develop cancer, likely telomerase-positive, late in life." (PMID 31552268, 2019). "Synthetic inhibition of FANCM-BTR complex formation is selectively toxic to ALT cancer cells." (PMID 31138797, 2019). "As such, FANCM represents an attractive target in ALT cancer therapy." (PMID 31138795, 2019). "Three of the identified mutations showed cosegregation with cancer (CHEK2, ERCC3 and FANCM)." (PMID 28050010, 2017). "In addition to cancer therapy, FANCM inhibition using our identified gapmers could be used to improve genome editing in vitro." (PMID 40125273, 2025). "Such compounds would create a dominant-negative form of FANCM that retains DNA binding and core complex recruitment while blocking its ability to process DNA structures—precisely the combination that previous studies suggested would be most toxic to cancer cells." (PMID 40447800, 2025). "RPA and RAD52 co-localized at the telomeres of ALT-positive cancer cells marked by telomere repeat binding factor 2 (TRF2), and their association with telomeres was further enhanced by replication stress or when ALT activity was increased by FANCM depletion, as has been demonstrated previously." (PMID 36894693, 2023). "FANCM loss of function causes early-onset cancers but not FA." (PMID 32962238, 2020). "However, the relative distribution of HR mutation among subtypes were varied, though all subtypes had relatively high rates of ATM, BRCA, and POLQ mutations, with FANCM mutations common to mucinous and non-specified carcinomas." (PMID 33214570, 2020). "Interestingly, a few apparently healthy (i.e., without cancer) individuals homozygous for the c.5101C>T FANCM mutation were identified in previous studies." (PMID 29231814, 2017). "Thus, FANCM-TONSL-MMS22L acts coordinately as a complex on chromatin that resolves replication stress, and this complex may present a therapeutic target for wildtype FANCM-linked cancer." (PMID 41030968, 2025). "We designed and screened several gapmers, identifying effective candidates that potently reduced FANCM expression, which led to an increased ALT activity and telomeric dysfunction, concomitant with a reduced viability of ALT-positive cancer cells." (PMID 40125273, 2025). "Future studies, possibly utilizing conditional knockout cells for FANCM and BLM, should refine this intriguing cellular scenario and open the way to novel avenues for curing ALT cancers." (PMID 31138795, 2019). "Targeting FANCM, more specifically its enzymatic activity or its interaction with the BTR complex, holds the potential for a successful treatment of ALT cancers." (PMID 31552268, 2019).